BRCA2 (BRCA2 DNA repair associated)
Diseases named in the same sentence as BRCA2 in open-access papers (continued):
Sharing a sentence is not in itself a finding about the gene and the disease.
tumor (continued). "We previously showed that BRCA mutation positive and BRCA mutation negative MBC cases display different phenotypic features, and in particular we identified a specific BRCA2-associated MBC phenotype characterized by higher tumor grade compared with MBC from the general population." (PMID 29731982, 2018). "For example, breast tumours from patients with germline mutations in BRCA1 or BRCA2 harbour a greater number of clonal mutations compared with BRCA1/2 wild-type tumours, and in a study of gastric cancer, an association between ATM loss and microsatellite instability has been demonstrated." (PMID 29123260, 2018). "Similar results were found in BRCA1- and BRCA2-associated tumours." (PMID 29665859, 2018). "From a biological rationale perspective, it is envisaged that PARP inhibitors are active irrespective of whether a BRCA1/2 variant is of germline or somatic origin as both result in the loss of function of both copies of BRCA1 or BRCA2 in the tumor." (PMID 29215764, 2018). "As another example, ctDNA analysis in BR28 showed that EGFR p.R521K and PTCH1 p.T1195S variants were more frequent than ATM pH1380Y, BRCA2 p.N289H, and BRCA2 p.N991D, whereas all these variants were present at a similar frequency in tumor tissue samples at diagnosis and after the 1st NAC cycle." (PMID 29156805, 2017). "Next-generation sequencing (NGS) done on a tumor biopsy was positive for the BRCA2 mutation." (PMID 28706762, 2017). "We thus reasoned that USP21 depletion and the associated reduction in BRCA2 may result in a similar tumor growth defect." (PMID 28743957, 2017). "To determine if the reduction in the growth of USP21-depleted tumor cells is functionally linked to the decrease in BRCA2 protein, we generated stable, BRCA2-transgenic HCC cell lines and followed clonogenic survival in the presence or absence of USP21 knockdown." (PMID 28743957, 2017). "Thus MED12L/MED12 amplifications are preferentially mutated in aggressive disease—both BRCA2-driven primary tumours and sporadic mCRPC." (PMID 28067867, 2017). "Moreover, treatment with acetaldehyde in BRCA1‐ and BRCA2‐deficient mouse tumor models and patient‐derived tumor xenografts in vivo results in regression of tumors." (PMID 28835508, 2017). "BRCA2 mutations promote tumour formation while also paradoxically causing cell lethality." (PMID 28904335, 2017). "Male BRCA2 mutation carriers more frequently had grades 2 and 3 tumours than grade 1 tumours, as compared with MBC cases from the general population (grade 2 vs. grade 1 OR 2.98, 95 % CI 1.44–6.19; grade 3 vs. grade 1 OR 5.53, 95 % CI 2.69–11.39; P for trend = 4.52 × 10−12)." (PMID 26857456, 2016). "In conclusion, taking into account the implications for both the individuals and their family members, we recommend that patients with these neoplasias should be offered BRCA1/BRCA2 genetic testing and we here show that it is feasible to test for founder mutations in archival tumor tissue." (PMID 27532258, 2016). "However, grade 3 tumours were more frequent among male BRCA2 mutation carriers diagnosed at younger ages (younger than age 50 years) than among those diagnosed at older ages, whereas grade 2 tumours showed an inverse trend." (PMID 26857456, 2016). "We predict that in addition to killing the tumour cells, PARPi may facilitate the survival of normal BRCA2 heterozygous cells that undergo loss of heterozygosity." (PMID 27498558, 2016). "The Brca2G25R/Ko;Palb2Ko/+ animals that result in the least interaction between BRCA2 and PALB2 and exhibited the shortest tumor latency, predominantly developed lymphoblastic T-cell lymphomas, similar to the mice carrying a truncating mutation in exon 11 of Brca2." (PMID 27490902, 2016). "However, in recent years it has become possible to exploit the DNA-repair defects in tumours carrying BRCA1 or BRCA2 gene mutations using PARP inhibitors." (PMID 27463681, 2016).
tumor (continued). "This represents an alternative approach to the use of FFPE materials for the identification of BRCA1 and BRCA2 tumor mutations which may be of germline or somatic origin." (PMID 27793035, 2016). "The decrease in survival and increase in tumor predisposition of Brca2G25R mutant mice on Palb2Ko/+ genetic background provides strong evidence to suggest that normal levels of interaction between BRCA2 and PALB2 is essential for tumor suppression." (PMID 27490902, 2016). "Moreover, it would be more interesting to study women with BRCA1 and BRCA2 mutations separately due to their differences in tumor characteristics." (PMID 27129401, 2016). "BRCA1 and BRCA2 are tumor suppressors that are commonly mutated or depleted in hereditary and sporadic breast cancers, and have important roles in homologous recombination (HR), a template directed pathway that accurately repairs DNA lesions affecting both strands of the DNA duplex." (PMID 27434671, 2016). "Deficiencies in Rad18, FANCD2, BRCA2, and Rad51 are all known to sensitize tumor cells to CPT." (PMID 26871286, 2016). "Thus, the requirement for BRCA2 in HDR in other tissues is consistent with BRCA2 mutations impacting tumour predisposition in multiple tissue types." (PMID 27779185, 2016). "Furthermore, the BRCA2 gene is located at chromosome 13q12, where a high frequency of allelic loss in tumours occurs." (PMID 25436004, 2015). "Moreover, we also observed that FOXA1 expression was significantly lower in BRCA1-mutated tumours compared with BRCA2, BRCAx and BRCA2/x tumours (P<0.001, P=0.001 and P<0.001, respectively; Student's t-test)." (PMID 25531315, 2015). "Moreover, the loss of two tumour suppressor genes Breast Cancer Susceptibility Gene 2 (BRCA2) or the LATS1 tumour suppressor is accompanied by cytokinesis defects, suggesting a role for these tumour suppressors during cytokinesis." (PMID 26491220, 2015). "However, ER-negative grade 3 tumor status was modestly predictive of positive BRCA2 mutation status in women diagnosed at 50 years or older (LR, 1.54; 95% CI = 1.27 to 1.88)." (PMID 25857409, 2014). "Moreover, several lines of evidence implicate mutations inactivating the BRCA2 tumour suppressor in an estimated 5–20% of familial PDAC." (PMID 24268522, 2014). "Tumours may also acquire resistance by additional mutations in the BRCA1 & BRCA2 gene and so there is a place for further investigation of DNA repair inhibition in HR defective tumours." (PMID 25526776, 2014). "Only determination of pathogenicity by a multifactorial likelihood model using independent data sources (e.g. segregation analysis, allele frequency, tumor pathology markers, co-occurrence, and co-observation with BRCA2 pathogenic variants) should be considered clinically." (PMID 24845084, 2014). "Therefore, we suspect that although MMR pathway is compensatorily activated in response to DSB-repair deficiency, BRCA1 tumours exhibit a weaker MMR pathway compared to BRCA2 tumours because of the direct involvement of BRCA1 in the MMR pathway." (PMID 25521701, 2014). "One very interesting study of tumor tissue derived from patients with BRCA2 mutations that had initially responded to olaparib but subsequently developed resistance revealed secondary mutations in the resistant tumors that restored BRCA2 function." (PMID 23802008, 2013). "Taken together, this observation suggests that BRCA2-deficient tumour cells may be predisposed to a more frequent incidence of indels in short repetitive sequences." (PMID 21750719, 2011). "Hence, the apparent differences in the strength of the SNP associations by BRCA1 and BRCA2 mutation status can be explained once tumour subtype is taken into account." (PMID 22053997, 2011).
tumor (continued). "On this basis we examined the immediate sequence context of the small indels detected in the Capan-1 genome, and compared these to the two BRCA2-deficient tumours sequenced in the Stephens dataset, in addition to the BRCA-proficient COLO-829 and COLO-829BL matched pair." (PMID 21750719, 2011). "Consistent with Knudson's two-hit hypothesis for tumor suppression, loss of the wild-type (wt) BRCA2 allele has been described as an essential event in tumor initiation in BRCA2 carriers." (PMID 21958427, 2011). "Loss of heterozygosity was found in the majority of tumours of BRCA2 mutation carriers." (PMID 20736950, 2010). "BRCA2-mutated tumours had a particularly high degree of methylation." (PMID 20565864, 2010). "Incorporating information on tumour pathology influences the predicted probabilities of carrying a BRCA1 or BRCA2 mutation, in particular BRCA1, and may therefore have implications for genetic testing and clinical decision-making." (PMID 20482762, 2010). "Hence, loss of BRCA2 is thought to principally lead to tumour progression by the failure to repair DNA by HR, leading to genomic instability." (PMID 20585617, 2010). "Previous reports in MZ twins with BRCA1 and BRCA2 mutations suggest that an analogous regulated program may also occur in other kinds of hereditary tumours." (PMID 20687928, 2010). "Interestingly, one sporadic tumour classified among the BRCA2-related subgroup, which was otherwise exclusively comprised of tumours derived from BRCA2 germline mutation carriers." (PMID 19589159, 2009). "Given the common roles of the BRCA gene products in genomic maintenance, this suggests that phenotypic differences between BRCA1- and BRCA2-associated tumours impose selective advantages for distinct genomic alterations in the context of instability generated by BRCA-deficiency." (PMID 19589159, 2009). "Consistent with the tumor suppressor status of the gene, tumors that develop in carriers of heterozygous BRCA2 mutations are frequently associated with loss of heterozygosity at the BRCA2 locus." (PMID 17945002, 2007). "Alternatively, if BRCA2 were primarily serving a role in genome maintenance (rather than in growth regulation or some other proper and expected "tumor-suppressor" function), its functional loss might often be selected against." (PMID 16417627, 2006). "The findings here provide further information specifically with respect to older BRCA1 and BRCA2 patients and warrant further studies for evaluating the probability of mutation by combining information on family history and tumour characteristics in the various age groups." (PMID 15987451, 2005). "Thus, a prevalence of 2.3–18.5% of occult tumours in BRCA1 or BRCA2 germline mutation carriers has been found." (PMID 15083174, 2004). "53% of these tumours showed a copy number loss of the BRCA2 gene by FISH." (PMID 11710835, 2001). "LOH was found in 65 tumours, which all showed simultaneously loss of BRCA2 and RB1." (PMID 7577475, 1995). "Consequently, the apparent differences in treatment outcomes between BRCA1 and BRCA2 carriers may be driven more by tumor phenotype than by the specific gene mutation itself." (PMID 41463210, 2025). "Overall, the gene expression analysis reveals that Brca2-deficient MBs have a gene expression program similar to P7 GCPs but also acquire additional expression changes that may promote tumor growth through pathways divergent from those active during normal GCP proliferation." (PMID 40854122, 2025).
tumor (continued). "Importantly, subgroup analyses stratified by BRCA mutation type (BRCA1 vs. BRCA2) and tumor biology (triple-negative vs. hormone receptor-positive) confirmed these findings, supporting the applicability of BCS across biologically distinct subgroups within the BRCA-mutated population." (PMID 41302125, 2025). "In humans, mutations in the BRCA1 and BRCA2 genes are strongly associated with an increased risk of breast, ovarian, prostate, pancreatic, melanoma, and peritoneal cancers, highlighting their essential role in DNA repair mechanisms, cell cycle control, and tumor suppression." (PMID 40004231, 2025). "Finally, we determined the effect of BRCA1 or BRCA2 loss on in vivo tumor growth." (PMID 39028933, 2024). "Several studies have identified the dependent pathways of BRCA2-deficient tumors that have undergone malignant transformation or their resistance mechanism to PARP inhibitor treatment by screening siRNA libraries or sgRNA libraries of BRCA2-deficient tumor cells." (PMID 37934606, 2024). "Therefore, BRCA-associated male tumours could be due to BRCA2 PVs different from those usually detected in women." (PMID 38974244, 2024). "Importantly, in previous studies, we found that PARG deficiency causes PARPi resistance in human BRCA2-deficient tumor cells and may contribute to PARPi resistance in patients." (PMID 38360994, 2024). "Importantly, four genes (MET, ATRX, ATR, and BRCA2) associated with active clinical trials were mutated specifically in one region of the tumours investigated, suggesting that may have been missed if tumour heterogeneity had not been considered." (PMID 39766052, 2024). "Additionally, BRCA Ashkenazi Jewish founder mutations (BRCA1 c.68_69delAG, BRCA1 c.5266_5267insC, or BRCA2 c.5946delT) were detected at similar rates across all subgroups, highlighting the need for further research to understand their role in tumor response to PARP inhibitors." (PMID 39272683, 2024). "In addition, strategies that further increased production of ROS by blocking alternate antioxidant pathways (i.e., TXNR) or compromising DNA repair (PARP inhibition; BRCA2 mutation) exacerbated this DNA damage leading to synergistic PCa cell killing and inhibition of PCa tumor growth." (PMID 37170264, 2023). "Thus, the mechanisms of transformation giving rise to HR− and HR+ tumours in BRCA2 mutation carriers may be distinct." (PMID 37626143, 2023). "Surprisingly, in both the Brca1- and Brca2-deficient tumour models used in this study, the in vivo treatment with anti-PD-L1, whether as a monotherapy or in combination with olaparib, resulted in a systemic increase in nearly all the studied immune cells presenting surface PD-L1." (PMID 38017453, 2023). "Moreover, while both BRCA1 and BRCA2 associated tumours have a homologous recombination repair deficiency, there are phenotypical characteristics which could lead to a different chemotherapeutic response." (PMID 34929424, 2022). "However, it is possible that reversion of an undetected second mutation in BRCA2 has occurred in the metastasis and therefore transient loss of BRCA2 expression in the past could explain the fact that this tumor was found HRD (BRCA2-type) by CHORD." (PMID 35662281, 2022). "In addition to patients with tumours containing BRCA1 or BRCA2 pathologic variants, there is emerging evidence that patients with tumours harbouring pathologic variants in other HR genes may also benefit from PARPi therapy." (PMID 36011309, 2022). "In addition, inherited BRCA1 or BRCA2 germline mutations may dramatically increase the risk of secondary tumors in “normal” tissue encompassing the tumor, which is also partly irradiated during radiotherapy." (PMID 35057061, 2022). "Additional practice changes, including BRCA1 and BRCA2 mutation testing by gynecologic oncologists and reflex tumor testing by the Department of Pathology, may also be evaluated in future years to determine their impact on detecting BRCA1/2 positivity (i.e., rates)." (PMID 36547149, 2022).
tumor (continued). "However, the most recurrent BRCA2 protein changes are the frameshift insertion N1784Kfs*3, the frameshift deletion K1691Nfs*15 and the missense mutation R2842C, which were detected in 3.4%, 2.72% and 2.04% of all BRCA2-mutated primary tumor samples in our analysis, respectively." (PMID 35158934, 2022). "Furthermore, curcumin reduced tumor growth in BRCA2-deficient cells following CPT-11 treatment." (PMID 33922657, 2021). "Rucaparib was also approved by the FDA for patients with deleterious BRCA1 or BRCA2 mutation (germline and/or somatic)‐associated mCRPC who have been treated with androgen receptor‐directed therapy and a taxane‐based chemotherapy based on the tumour testing findings of the TRITON2 study." (PMID 33630412, 2021). "Indeed, BRCA2-deficient tumor cells rely on FANCD2 for fork protection and cell survival." (PMID 34440403, 2021). "Thus, genetic screens to identify either germline or somatic BRCA2 mutations in the tumor, which could sensitize a variety of tumor types to different therapeutic agents, hold promise for guiding the selection of tailored treatment options." (PMID 34356050, 2021). "Furthermore, among the 15 patients with loss-of-function of BRCA1/2 (nine tumors with BRCA1 hypermethylation, five tumors with BRCA1 mutation and one tumor with BRCA2 mutation), SigMA identified ten to be Sig3 positive, again consistent with the reported sensitivity of the SigMA algorithm." (PMID 32193378, 2020). "As an example, we do not observe significant differences in CpG methylation between BRCA2-mutated tumours vs sporadic ones, but, at the same time, power analysis reveals reduced statistical power for this comparison, and we may be led to different conclusions with larger datasets." (PMID 31182087, 2019). "Besides, women with BRCA1 or BRCA2 mutations presented different tumor and FH profiles." (PMID 31244284, 2019). "Interestingly, a statistically significant decrease in Rad51 foci was observed in Brca2 heterozygous carriers compared to wild types, indicative of haploinsufficiency, a hypothesised cause of some tumours in patients with a germline BRCA2 mutation." (PMID 29184099, 2017). "For example, in the presence of BRCAness, a tumor with a miRNA down-regulated BRCA2 can have similar clinical features as a tumor with BRCA2 germline mutations: in such a case, patients from either group would have similar prognosis and may require similar adjuvant or neoadjuvant therapies." (PMID 27630665, 2016). "In contrast to FA, HR factors including RAD51, RAD51 paralogs and BRCA2 are required for telomere replication and capping and thus the genomic instability characteristic of HR‐deficient cells and tumours may have a telomere dysfunction component." (PMID 27037238, 2016). "As patients with tumours that harbour a somatic BRCA mutation may also benefit from treatment with PARP inhibitors, it is important to be able to test for BRCA1 and BRCA2 variants in tumour samples available after routine histopathology assessment and diagnosis." (PMID 25859162, 2015). "However, age-stratified analysis highlighted that ER-negative grade 3 tumor status modestly predicted positive BRCA2 mutation status in women diagnosed at age 50 years or older, indicating that grade is a more important factor than ER status in predicting BRCA2 tumors." (PMID 25857409, 2014). "However, the sensitivity and reliability of such biomarkers may be complicated by mutations in the BRCA1 or BRCA2 genes, diverse genetic risk factors, unidentified initiation and progression elements, molecular tumor heterogeneity and disease staging." (PMID 22481932, 2012).